NUF2 (NUF2 component of NDC80 kinetochore complex)
Description:
Acts as a component of the essential kinetochore-associated NDC80 complex, which is required for chromosome segregation and spindle checkpoint activity. Required for kinetochore integrity and the organization of stable microtubule binding sites in the outer plate of the kinetochore. The NDC80 complex synergistically enhances the affinity of the SKA1 complex for microtubules and may allow the NDC80 complex to track depolymerizing microtubules.
Synonyms: CDCA1; NUF2R; CT106
Tractability: Small molecule: a structure with a bound ligand is known. PROTAC: ubiquitination databases record sites on it.
Gene: Protein-coding gene on chromosome 1 (163,266,576 to 163,355,766, forward strand). Ensembl gene ENSG00000143228.
Subcellular location: Nucleus; Chromosome, centromere, kinetochore
Subcellular location (Human Protein Atlas): Nucleoplasm; Cytosol; Kinetochore
Pathways (Reactome):
Cell Cycle: Amplification of signal from unattached kinetochores via a MAD2 inhibitory signal; EML4 and NUDC in mitotic spindle formation; Mitotic Prometaphase; Resolution of Sister Chromatid Cohesion; Separation of Sister Chromatids
Signal Transduction: RHO GTPases Activate Formins
Gene Ontology:
Molecular function: microtubule binding; protein binding; protein-containing complex binding
Biological process: attachment of spindle microtubules to kinetochore; attachment of mitotic spindle microtubules to kinetochore; chromosome segregation; kinetochore organization; meiotic chromosome segregation; mitotic spindle assembly checkpoint signaling
Cellular component: kinetochore; membrane; Ndc80 complex; nucleoplasm; outer kinetochore; cytosol; nucleus
Genetic constraint (gnomAD): Loss-of-function variants: 10 observed, 17.16 expected, observed/expected ratio (o/e) 0.58, 90% interval 0.36 to 0.99. The upper end of that interval is the gene's LOEUF score, 0.99, which puts it in group 4 of 6, group 1 being the genes least tolerant of losing a copy. Missense variants: 141 observed, 165.82 expected, observed/expected ratio (o/e) 0.85, 90% interval 0.74 to 0.98. Synonymous variants: 55 observed, 61.11 expected, observed/expected ratio (o/e) 0.9, 90% interval 0.72 to 1.13.
Homologues: Orthologues: chimpanzee NUF2 (100% identical), macaque NUF2 (100% identical), pig NUF2 (92% identical), rabbit NUF2 (92% identical), dog NUF2 (89% identical), guinea pig NUF2 (89% identical), rat Nuf2 (79% identical), mouse Nuf2 (73% identical), tropical clawed frog nuf2 (44% identical), zebrafish nuf2 (33% identical). Paralogues in human: TMEM259 (12% identical).
Diseases named in the same sentence as NUF2 in open-access papers:
NUF2 is named in the same sentence as 69 diseases in open-access papers, as found by Europe PMC text mining. Sharing a sentence is not in itself a finding about the gene and the disease. The quoted sentences say what the papers report.
breast cancer (23 papers, 2014 to 2025). A primary or metastatic malignant neoplasm involving the breast. "It was also found that poor breast cancer patient survival was significantly associated with high NUF2 expression caused by low TTP/HuR mRNA ratios." (PMID 36670423, 2023). "The ROC curve of NUF2 was analyzed to investigate the diagnostic significance of NUF2 in differentiating breast cancer samples from normal samples." (PMID 36835637, 2023). "For example, NUF2 mRNA is significantly upregulated in breast cancer, and upregulated NUF2 is significantly associated with malignant features and poor prognosis." (PMID 36620547, 2022). "Another study suggested that cell cycle analysis revealed that NUF2 induced G0/G1 cell cycle arrest by inhibiting cyclin B1 expression in breast cancer." (PMID 40220284, 2025). "Many reports have identified NUF2 as an oncogene in various cancers, including clear cell renal cell carcinoma, melanoma, and breast cancer." (PMID 39703688, 2024). "NUF2 is an oncogene that reported in clear cell renal cell carcinoma 30, melanoma 31, hepatocellular carcinoma 32, and breast cancer." (PMID 37056930, 2023). "Overall, we found that the main pathway in which NUF2 is involved in breast cancer is cell proliferation, and NUF2 promotes cell proliferation." (PMID 36835637, 2023). "The same results were obtained by Western blot, and the expression level of the NUF2 protein was significantly upregulated in the breast cancer cell lines." (PMID 36835637, 2023). "We found that NUF2 expression was higher in the breast cancer cell lines MCF-7 and SKBR3 and the triple-negative breast cancer cell lines MDA-MB-231, Hs-578T, and MDA-MB-452 compared to the normal breast epithelial cells MCF-10A." (PMID 36835637, 2023). "This study explored the role of NUF2 in breast cancer development and prognosis using informatic analysis combined with in vivo intracellular studies." (PMID 36835637, 2023). "Gene set enrichment analysis was used to investigate the potential mechanism of NUF2 in regulating breast cancer." (PMID 36835637, 2023). "Previous studies have also found that knockdown of NUF2 induces cell cycle arrest in pancreatic cancer and breast cancer." (PMID 35814368, 2022). "Mounting evidence suggests that NUF2 is a valuable prognostic biomarker for detecting breast cancer, hepatocellular carcinoma, and oral cancer." (PMID 35814368, 2022). "NUF2 overexpression can increase the proliferative ability of liver, pancreatic, and breast cancer cells." (PMID 35814368, 2022). "Accumulating evidence has indicated that NUF2 expression is upregulated in a series of human cancers, including colorectal 14, stomach 14, oral cancers 24, breast cancer 25, and osteosarcoma 26, and that the depletion of NUF2 suppresses cancer cell growth." (PMID 35813477, 2022). "For instance, NUF2 knockdown inhibited cell proliferation and colony formation and induced apoptosis in breast cancer." (PMID 36620547, 2022). "Our study showed that ASPM, INHBA, NUF2, ORC6, UBE2T and PKMYT1 are associated with cell proliferation, and the expressions of these genes were also elevated in our breast cancer tissue transcriptome." (PMID 31182966, 2019). "Cluster 2 (KIF2C, NDC80, NUF2) is also in agreement with the molecular subtypes and has the expression pattern similar to Cluster 1 in breast cancer patients." (PMID 31260503, 2019). "TYMS is also a target gene of three Breast cancer drugs (Fluorouracil, Gemcitabine and Capecitabine) and physically interacts with two genes from the Triple Negative pattern -NUF2 and NDC80." (PMID 26892392, 2016). "For example, NUF2 was identified as a new cancer stem cell indicator in breast cancer." (PMID 39242581, 2024). "Additionally, the Mann–Whitney U test and logistic regression analysis were used for the analysis, which aimed to evaluate the relationship between NUF2 mRNA expression and the clinicopathological features of the breast cancer samples." (PMID 36835637, 2023).
breast cancer (continued). "Through functional enrichment and PPI protein network analysis, we found that NUF2 may promote breast cancer tumor development by participating in cell division and cell cycle regulation." (PMID 36835637, 2023). "The expression profile was constructed to detect the expression of NUF2 in breast cancer." (PMID 36835637, 2023). "Since the efficacy and prognosis of endocrine therapy for breast cancer were closely related to the hormone receptor expression level, NUF2 may be a biomarker for the diagnosis of BRCA." (PMID 36835637, 2023). "Moreover, NUF2 contributes to the malignant progression of tumor, including colorectal cancer, gastric cancer, pancreatic cancer, breast cancer, and renal clear cell carcinoma." (PMID 36620547, 2022). "In addition, NUF2 is elevated in breast cancer, human osteosarcoma, pancreatic tumor, and colorectal cancer and is an important diagnostic, treatment, and prognostic marker of tumors." (PMID 35600043, 2022). "NUF2 may regulate the carcinogenesis and progression of breast cancer via ‘cell cycle’ related pathways." (PMID 34053447, 2021). "Recent studies have shown that NUF2 was also closely related to breast cancer." (PMID 33005492, 2020). "Through the qRT-PCR detection of breast cancer cell lines, we found that the expression of NUF2 was upregulated in breast cancer cell lines compared to normal breast epithelial cells, MCF-10A." (PMID 36835637, 2023). "These experimental results suggest that NUF2 may serve as one of the indicators of tumor stemness not only in breast cancer but also in other cancers." (PMID 36835637, 2023). "As a result, both NUF2 and TXNIP protein levels were downregulated in breast cancer cells lacking STARD7." (PMID 40443279, 2025).
hepatocellular carcinoma (15 papers, 2017 to 2023). A malignant tumor that arises from hepatocytes. "Up-regulated NUF2 has been reported to be associated with poorer prognosis in patients with hepatocellular carcinoma and non-small cell lung cancer." (PMID 37138262, 2023). "NUF2, a prognostic-associated marker, is correlated with infiltrations of immune cells in hepatocellular carcinoma." (PMID 35600043, 2022). "In hepatocellular cancer, Xie found that high expression of NUF2 was correlated with poor survival and differential immune cell infiltration in patients." (PMID 36670423, 2023). "In previous studies, Erb-B2 receptor tyrosine kinase 2 (ERBB2) and NUF2 component of the NDC80 Kinetochore Complex (NUF2) were reported to be biomarkers of hepatocellular carcinoma (HCC) recurrence after surgery." (PMID 34956309, 2021). "Previous studies have shown that NUF2 is an effective prognostic molecule for hepatocellular carcinoma 30, and silencing NUF2 can suppress human hepatocellular carcinoma tumor growth and induce apoptosis." (PMID 33403046, 2021). "NUF2 is a direct target of miR-3613-3p which participate in cell proliferation and cell cycle in hepatocellular carcinoma." (PMID 30718521, 2019). "High levels of CDCA1 (also known as NUF2, NDC80 kinetochore complex component), KNTC2 (kinetochore associated 2), SPC24, and SPC25 have been found to be correlated with colorectal and hepatocellular carcinoma tumors." (PMID 29029446, 2017). "The NDC80 complex is composed of four components, comprising NDC80, NUF2, SPC24, and SPC25, and aberrant expression of these four components may cause uncontrolled cell proliferation in hepatocellular carcinoma." (PMID 38102624, 2023). "Additionally, NUF2 can be used as a molecular marker to predict tumor progression in oral cancer 24, hepatocellular carcinoma 27, and lung cancer 28, among other cancers." (PMID 35813477, 2022). "However, the mechanism and function of Nuf2 in the development of Hepatocellular carcinoma (HCC) remains uncertain." (PMID 33767990, 2021). "In the study, we found that therapy target genes of Jianpi Jiedu decoction were mainly involved in metabolism and apoptosis in hepatocellular carcinoma, and there was a close relationship between the prognosis of hepatocellular carcinoma and the genes of CCNB1, NQO1, NUF2, and CHEK1." (PMID 33424998, 2020). "The NUF2 gene is also known to be consistently overexpressed in human hepatocellular carcinoma tissues; its sufficient expression ensured the appropriate growth of hepatocellular carcinoma cells, which may have a negative impact on animal health." (PMID 36496924, 2022).
colorectal cancer (13 papers, 2017 to 2024). A primary or metastatic malignant neoplasm that affects the colon or rectum. "NUF2 has been reported to be associated with several human cancers including lung cancer, colorectal cancer, and prostate cancer." (PMID 30718521, 2019). "The results showed that the expression of NUF2 was associated with poor prognosis in patients with colorectal cancer and oral cancer, which may be related to the regulation of tumor cell apoptosis involved in the NUF2." (PMID 33005492, 2020). "NUF2 plays an important role in tumorigenesis and is upregulated in multiple human cancers, including serous adenocarcinoma, liver cancer, colorectal cancer, pancreatic cancer, ovarian cancer, lung cancer, gastric cancer and bladder cancer." (PMID 37138262, 2023). "NUF2 plays an important role in tumorigenesis and is upregulated in multiple human cancers, including serous adenocarcinoma, liver cancer, and colorectal cancer." (PMID 37762324, 2023). "NUF2 is a novel cancer biomarker overexpressed in lung cancer, colorectal cancer and pancreatic cancer." (PMID 31788359, 2019). "Except for the testis, dysregulation of NUF2 has been reported in the development of several human cancers, including lung cancer, colorectal cancer, prostate cancer, as compared to normal tissue." (PMID 29190974, 2017). "In colorectal cancer, studies have found that heterogeneous nuclear ribonucleoprotein K activated the transcription of NUF2, knockdown of NUF2 expression could significantly inhibit proliferation of colorectal cancer cells." (PMID 36670423, 2023). "Additionally, inhibiting the expression of Nuf2 can slow down the growth of glioma, liver cancer, colorectal cancer, and gastric cancer." (PMID 35393397, 2022). "Likewise, NUF2 knockdown by siRNA significantly inhibited cell proliferation and induced apoptosis in colorectal cancer and gastric cancer cells." (PMID 36620547, 2022). "In particular, MYC, MAD2L1, CENPF, UBE2C, NUF2 and NCAPG2 were identified as highly expressed in colorectal cancer samples." (PMID 38637125, 2024). "The core genes, namely MYC, MAD2L1, CENPF, UBE2C, NUF2 and NCAPG2, showed elevated expression in colorectal cancer samples, in stark contrast to their comparatively lower expression in normal samples." (PMID 38637125, 2024). "Notably, the core genes (MYC, MAD2L1, CENPF, UBE2C, NUF2, NCAPG2) had differential expression in colorectal cancer samples in comparison to normal samples." (PMID 38637125, 2024).
liver cancer (13 papers, 2017 to 2023). An epithelial or non-epithelial malignant neoplasm that arises from the liver. "Silencing of NUF2 suppresses an in vitro cell proliferation and inhibits tumor growth in pancreatic and liver cancers." (PMID 36499051, 2022). "Studies have found that NUF2 is highly expressed in a variety of malignant tumors, including lung cancer, liver cancer, CRC, and gastric cancer, and plays an important role in tumor formation and development." (PMID 35149954, 2022). "Small interfering RNA inhibited NUF2 expression in pancreatic cancer, glioma, and liver cancer and reduced the growth of tumors." (PMID 34260414, 2021). "In terms of liver cancer, some experiments have shown that the expression of NUF2 in human liver cancer tissues is significantly higher than that in adjacent normal tissues, and there is also a high expression in liver cancer cell lines." (PMID 33424998, 2020). "Moreover, the proliferation and invasion of liver cancer cells can be inhibited by targeted knockdown of NUF2, indicating that the up-regulated NUF2 is closely related to a poor prognosis in tumors." (PMID 37138262, 2023). "Next, Cox relative risk model is used to examine Whether NUF2 and BLM can become independent diagnostic influence factor for 95 patients suffering from liver cancer in our center." (PMID 32565735, 2020). "High expression of NUF2 can promote the growth and inhibit the apoptosis of liver cancer cells." (PMID 33424998, 2020). "Immunohistochemical experiments were performed, and the results shown that NUF2 may play an pivotal role in promoting the occurrence and development of liver cancer, but the mechanism needs more research to demonstrate and and this is what we are doing." (PMID 32565735, 2020). "We found that BIRC5, CDK1, NUF2, ZWINT, and SPC24 were highly expressed in liver cancer tissues, whereas expression was weak in normal tissues." (PMID 29190974, 2017). "Therefore, we can think that nuf2 and BLM can provide independent prediction for liver cancer patients." (PMID 32565735, 2020). "Our data shows that BIRC5, NUF2, and SPC24 may be promising liver cancer biomarkers that may not only predict disease occurrence but also potential personalized treatment options." (PMID 29190974, 2017). "Therefore, we suggested that BIRC5, NUF2, and SPC24 may be promising biomarkers in human liver cancer that provide information not only for predicting disease occurrence but also for suggesting personalized treatment options." (PMID 29190974, 2017).
lung carcinoma (13 papers, 2013 to 2024). "Thus, we investigated the association between NUF2 expression in lung cancer tissues and dissected lymph nodes and early recurrence of NSCLC to determine its usefulness as a marker of lymph node micrometastasis." (PMID 38472943, 2024). "CDC34, which is upregulated in B-ALL EVs, is known to facilitate lung cancer progression, while NUF2, which is upregulated in the EVs of 6 of 8 B-ALL samples in this study, is known to facilitate the progression of lung adenocarcinoma." (PMID 38023151, 2023). "It was demonstrated that the expression of NUF2 in lung cancer tissues was significantly higher than that in the corresponding paired para-tumor tissues, and the subcellular localization of NUF2 protein was in the nucleus and cytoplasm." (PMID 35814368, 2022). "The present study identified and validated NUF2, KIF4A, KIF18B, DLGAP5, NEK2, and LRRK2 as promising diagnostic biomarkers for lung cancer." (PMID 36499051, 2022). "Overall, our findings provide a more detailed picture of the regulation of NUF2 in lung cancer and indicate that its expression can independently predict the DSS and PFS outcomes in LUAD patients." (PMID 36499051, 2022). "Analysis of NUF2 expression in dissected lymph nodes may predict postoperative lymph node recurrence in early-stage lung cancer and determine the indication for adjuvant chemotherapy after surgery." (PMID 38472943, 2024). "NUF2 is a tumor-specific antigen that is highly expressed in lung cancer tissues." (PMID 38472943, 2024). "NUF2 emerges as a promising marker for predicting lymph node metastatic recurrence, offering potential utility in guiding post-surgical adjuvant therapy for lung cancer or assisting in intraoperative decisions for sublobar resection." (PMID 38472943, 2024). "In lung cancer, Chen showed that upregulated NUF2 gene expression level probably played a crucial part in oncogenesis, and could be used as the potential prognostic marker to improve survival rate of the patients." (PMID 36670423, 2023). "NUF2 is a key regulator of the cell cycle and is overexpressed in several types of cancers, including bladder cancer, renal cell carcinoma, cholangiocarcinoma, and lung cancer." (PMID 35814368, 2022). "Furthermore, NUF2 knockdown was shown to induce cell death and cell invasion in lung cancer cell lines, indicating the potential role of NUF2 in lung cancer progression." (PMID 36499051, 2022). "For the first time, we propose NUF2, KIF4A, KIF18B, DLGAP5, NEK2, and LRRK2 as biomarkers for lung cancer progression." (PMID 36499051, 2022). "Here, NUF2, KIF4A, and KIF18B were commonly upregulated, and LRRK2 was commonly downregulated in both lung cancer subtypes." (PMID 36499051, 2022). "NUF2 is a good candidate for a new marker for detecting lymph node metastasis because it is frequently expressed in lung cancer tissue and not in lung and other normal tissues." (PMID 38472943, 2024).